SLC7A5 (solute carrier family 7 member 5)
Diseases named in the same sentence as SLC7A5 in open-access papers (continued):
Sharing a sentence is not in itself a finding about the gene and the disease.
triple-negative breast carcinoma (3 papers, 2019 to 2025). An invasive breast carcinoma which is negative for expression of estrogen receptor (ER), progesterone receptor (PR), and human epidermal growth factor receptor 2 (HER2). "In addition, amino acid transporter proteins such as SLC1A5 and SLC7A5 are overexpressed in the triple-negative breast cancer samples, enabling tumor cells to meet the high demand for amino acids." (PMID 37731509, 2023). "Furthermore, we also detect the expression of SLC7A5 in 10 fresh triple-negative breast cancer issue and their comparing nontumor-adjacent tissue, and it was revealed that SLC7A5 was higher expression in tumor tissues than nontumor-adjacent tissues." (PMID 37731509, 2023).
acute myeloid leukemia (2 papers, 2025). Acute myeloid leukemia (AML) is a group of neoplasms arising from precursor cells committed to the myeloid cell-line differentiation. "The results demonstrated that SLC3A2 and SLC7A5 were significantly enriched in ribosome, acute myeloid leukemia, insulin signaling pathway, olfactory transduction, etc.." (PMID 40420260, 2025).
allergic disease (2 papers, 2025). An immune response that occurs following re-exposure to an innocuous antigen, and that requires the presence of existing antibodies against that antigen. "Finally, multi-omics analysis of five independent allergic patient cohorts revealed that in severe allergy there is an impairment of SLC7A5-dependent transport of Phe into Th2 cells and an increase in its intracellular processing, leading to expansion of pathogenic Th2 cells." (PMID 41308641, 2025). "We noted that SLC7A5 (LAT1), SLC7A8 (LAT2), and SLC3A2 (CD98), part of LAT1 and LAT2 heterodimer complexes, were significantly downregulated in allergic asthma but not in allergic rhinitis, suggesting decreased transport of Phe into the Th2 cells in more advanced allergic disease." (PMID 41308641, 2025).
Intellectual disability (2 papers, 2020 to 2021). "Therefore, variants in SHANK genes together with the absence of rs113883650 variant in the LAT1 (SLC7A5) in our patients may work together to bring protection from the intellectual disability." (PMID 34900593, 2021).
ischemic stroke (2 papers, 2019 to 2022). A stroke disorder caused by obstruction of blood flow to the brain, due to thrombotic (local blood clot formation) or embolic (due to a blood clot or other material traveling from another site) event. "There is convincing evidence that Slc7a5 is deeply involved in the occurrence of ischemic stroke." (PMID 35485294, 2022). "In this study, we investigated whether Slc7a5 is regulated by hypoxia to mimic an ischemic stroke environment in neuronal cells, and the molecular mechanisms underlying the regulation of the expression of Slc7a5." (PMID 30761250, 2019).
liver fibrosis (2 papers, 2024). "There were similar results in single-gene GSEA analysis of SLC1A5, and both SLC1A5 and SLC7A5 were closely related to alcoholic liver disease, which is known as a common genesis of liver fibrosis around the world." (PMID 39698464, 2024). "Moreover, the knockdown of SLC7A5 expression in E2F2M‐KO mice using AAV‐SLC7A5 reduced the extent of liver fibrosis in those mice subjected to HFD." (PMID 39465673, 2024). "Then we speculate that immune checkpoints might correlate with HSC activation and liver fibrosis and found that SLC1A5 was significantly negatively associated with CTLA4, LAG3, and PDCD1; similarly, SLC7A5 was significantly negatively associated with CTLA4 and LAG3." (PMID 39698464, 2024). "Taken together, we automatically hypothesized that upregulated SLC7A5 and SLC1A5 might contribute to the development of liver fibrosis by suppressing the expression of the immune checkpoint and inducing the anomalous immunocyte activation intrahepatic." (PMID 39698464, 2024).
mastitis (2 papers, 2021 to 2026). Inflammation of breast tissue during lactation or postpartum due to an obstructed duct or infection. "Comparing genes that express at a different level and the protein network, we identified three key genes (CDKN1A, FKBP5 and SLC7A5) and pathways that mastitis includes both in clinical and subclinical form." (PMID 42127079, 2026).
metastatic diseases (2 papers, 2021). "SLC7A5 is an anti-glutamine transporter and is important in models of colorectal tumorigenesis in early and late metastatic diseases." (PMID 34522968, 2021).
microcephaly (2 papers, 2020). A congenital or acquired developmental disorder in which the circumference of the head is smaller than normal for the person's age and sex. "Pathogenic mutations in the solute carrier family 7 member 5 (SLC7A5) gene, which encodes an amino acid transporter cause microcephaly and seizures, yet the mechanisms responsible for these phenotypes are unclear." (PMID 32821949, 2020). "Inactivating mutations in the solute carrier family 7 member 5 (SLC7A5) gene lead to a neurodevelopmental disorder characterized by microcephaly, seizures and neuropsychiatric manifestations." (PMID 32821949, 2020). "OBs of the electroporated mice were next examined because neurons do not develop properly in Slc7a5 knockout mice and because patients with Slc7a5 mutations have microcephaly." (PMID 32821949, 2020).
non-Hodgkin lymphoma (2 papers, 2021 to 2022). Distinct from Hodgkin lymphoma both morphologically and biologically, non-Hodgkin lymphoma (NHL) is characterized by the absence of Reed-Sternberg cells, can occur at any age, and usually presents as a localized or generalized lymphadenopathy associated with fever and weight loss. "In Non-Hodgkin lymphoma, SLC7A5 expression was also significantly upregulated and was inversely correlated with patient survival span." (PMID 35986300, 2022).
oral cancer (2 papers, 2013 to 2020). "Of these, NTRK3 and SLC7A5 were earlier identified to be associated with oral cancer." (PMID 33317464, 2020).
Parkinson’s (2 papers, 2021 to 2023). "SLC7A5 plays an important role in the treatment of Parkinson’s disease by facilitating the transport of exogenous L-DOPA." (PMID 37907966, 2023).
renal carcinoma (2 papers, 2019 to 2022). A carcinoma arising from the epithelium of the renal parenchyma or the renal pelvis. "Together with the re-expression of key proteins that belong to BCAA catabolism, the reduction of SLC7A5 mRNA upon VHL re-expression confirmed that VHL loss is involved, at least in part, in the reprogramming of the BCAA degradation in renal cancer cells." (PMID 36539415, 2022).
squamous cell carcinoma (2 papers, 2024 to 2025). A carcinoma arising from squamous epithelial cells. "Gene SLC7A5 is upregulated in actinic keratosis and squamous cell carcinoma." (PMID 41199193, 2025). "Notably, we identified a malignant cell subpopulation expressing high levels of the key oncogenic driver gene TP63 in squamous cell carcinoma, known as TP63+ SLC7A5+ HNSCC." (PMID 39234254, 2024).
type 2 diabetes (2 papers, 2023 to 2024). "Genes annotated to CpGs that were associated with type 2 diabetes included ABCA1, ABCG1, CPT1A, SREBF1, SLC7A11, SLC7A5, and TXNIP among others (see S12 Table for full details)." (PMID 37410739, 2023).
ulcerative colitis (2 papers, 2020 to 2025). An inflammatory bowel disease involving the mucosal surface of the large intestine and rectum. "In conclusion, the ferroptosis-associated marker SLC7A5 emerges as a pivotal focus in elucidating the mechanism underlying ulcerative colitis (UC)." (PMID 40729322, 2025). "Immunohistochemical analysis further demonstrated increased SLC7A5 expression in DSS-induced ulcerative colitis mice, suggesting its potential role in pathogenesis." (PMID 40729322, 2025). "Supported by experimental validation, this investigation reveals a heightened expression of SLC7A5 in the ulcerative colitis (UC) group compared to the normal control group, underscoring a significant association between the gene and UC pathology." (PMID 40729322, 2025). "The results indicate that the differential expression of ACSF2 and SLC7A5 may serve as valuable biomarkers for the early diagnosis of ulcerative colitis." (PMID 40729322, 2025).
acute leukemia (1 paper, 2016). A clonal (malignant) hematopoietic disorder with an acute onset, affecting the bone marrow and the peripheral blood. "Our previous study identified a subset of six genes associated with the evolution of MDS to acute leukemia, including SLC7A5." (PMID 26657287, 2016).
age-related hearing loss (1 paper, 2021). "In addition, mutations in SLC7A5 and SLC7A8 (LAT1 and LAT2, respectively) cause autism-related disorders and contribute to age-related hearing loss and cataracts, respectively." (PMID 34436365, 2021).
aneurysmal disease (1 paper, 2019). "Additionally, FDC-SP and solute carrier family 7 member 5 (SLC7A5) were selected as they had not previously been associated with aneurysmal disease." (PMID 31683995, 2019). "In this AAA gene list we identified previously AAA-associated genes COL11A1, ADIPOQ, and LPL, thus validating our approach as well as novel genes; CXCL13, SLC7A5, FDC-SP not previously linked to aneurysmal disease." (PMID 31683995, 2019).
Arthritis (1 paper, 2020). Inflammation of a joint. "Downregulated or blocked SLC7A5 in FLS could serve as an anti-inflammatory molecule and a potential therapeutic target in arthritis." (PMID 32867828, 2020).
atherosclerosis (1 paper, 2025). A disease characterized by the build-up of fatty material and calcium deposition in the arterial wall resulting in partial or complete occlusion of the arterial lumen. "Leucine transporter-SLC7A5-mediated leucine intake that promotes advanced atherosclerosis in mice, increasing apoptotic macrophages and lipids accumulation within plaques." (PMID 41270215, 2025).
atopic dermatitis (1 paper, 2024). "There was a high expression of SLC7A5 in CD4 T cells in atopic dermatitis skin with T-cell activation." (PMID 38790003, 2024).
autoimmune hepatitis (1 paper, 2025). Hepatitis caused by autoantibodies. "In autoimmune hepatitis (AIH), GLS antagonists like JHU083 and DON not only attenuate T cell activation and reduce the Th1/Th17 ratio but also downregulate SLC7A5 mRNA expression, further dampening mTOR pathway activation." (PMID 40155378, 2025).
basal cell carcinoma (1 paper, 2025). A carcinoma involving the basal cells. "LAT1/SLC7A5 and LAT2/SLC7A8 are upregulated in basal cell carcinoma." (PMID 41002986, 2025).
chordoma (1 paper, 2023). Chordomas are rare malignant tumors arising from embryonic remnants of the notochord in axial skeleton. "Genes were selected to represent both those functionally connected to other chordoma dependency genes (PTPN11, FANCM, ADAR, PRKRA, SOX9, SRRM2, SLC2A1, and SLC7A5), as well as those with putatively unique effects (LUC7L2 and CDK6)." (PMID 37024492, 2023).
Cirrhosis (1 paper, 2021). A chronic disorder of the liver in which liver tissue becomes scarred and is partially replaced by regenerative nodules and fibrotic tissue resulting in loss of liver function. "The expression of SLC7A5/LAT1 was increased in patients with cirrhosis and it seems to play a role in increasing leucine uptake." (PMID 33803020, 2021).
colorectal tumor (1 paper, 2021). "Eventually, our in vitro findings are reinforced by the analysis of the TCGA gene expression datasets, showing that selected AATs (SLC1A5/ASCT2, SLC7A5/LAT1, and SLC38A2/SNAT2) are significantly upregulated in primary colorectal tumor tissues, compared with normal tissues." (PMID 34003553, 2021).
cutaneous melanoma (1 paper, 2025). A primary melanoma arising from atypical melanocytes in the skin. "LAT1/SLC7A5 was identified as a prognostic factor for poor outcome of cutaneous melanoma." (PMID 41002986, 2025).
diabetic retinopathy (1 paper, 2022). "A recently published study reported that SLC7A5 could be inhibited by empagliflozin, which ameliorates diabetic retinopathy manifestations." (PMID 36557283, 2022).
end-stage renal diseases (1 paper, 2018). "Of note, enhanced SLC7A5 expression was also observed in peripheral monocytes from patients with gout and end-stage renal diseases (data not shown), suggesting that this induction is a general feature of inflammatory monocytes to fulfill high metabolic demands during immune responses." (PMID 29422900, 2018). "IL-1β-mediated upregulation of SLC7A5 expression without any obvious external stimuli (e.g., TLR triggering) could explain the increase in SLC7A5 seen in monocytes from patients with inflammatory diseases, such as RA and end-stage renal diseases (data not shown)." (PMID 29422900, 2018).
endometritis (1 paper, 2020). An acute or chronic, usually bacterial infectious process affecting the endometrium. "This study confirmed differences in the expression profiles of six biomarkers in LPS-induced bovine endometritis: SLC7A5, COL1A1, AXIN2 (upregulated) and CFD, MGP, CCDC3 (downregulated)." (PMID 32545766, 2020). "The results revealed the dysregulation of the six crucial biomarkers involved in endometritis: SLC7A5, COL1A1, AXIN2 (upregulated); CFD, MGP, CCDC3 (downregulated)." (PMID 32545766, 2020).
Epileptic encephalopathy (1 paper, 2018). A condition in which epileptiform abnormalities are believed to contribute to the progressive disturbance in cerebral function. "In contrast, epileptic encephalopathy-linked mutations of Kv1.2 (R297Q and L298F) enhance susceptibility to the gating effects of Slc7a5." (PMID 30356053, 2018).
esophageal squamous cell carcinoma (1 paper, 2021). Esophageal squamous cell carcinoma (ESCC) is a type of esophageal carcinoma (EC) that can affect any part of the esophagus, but is usually located in the upper or middle third. "In esophageal squamous cell carcinoma (ESCC), circ-SLC7A5 was significantly up-regulated in the plasma of ESCC patients and high levels of circ-SLC7A5 are correlated with shorter survival time." (PMID 34239354, 2021).
hearing loss (1 paper, 2024). "Although differentially expressed genes associated with hormone transport are expressed in SGNs, including Slc7a5 and Syt7 as well as Spp1, their link to hidden hearing loss is less clear." (PMID 39049179, 2024).
hepatitis B virus infection (1 paper, 2015). A viral infection caused by the hepatitis B virus. "At certain circumstances, such as hepatitis B virus infection, T cells may upregulate SLC7A5 expression to meet the requirement for Leu and metabolic reprograming." (PMID 26439699, 2015).
iron deficiency (1 paper, 2021). "Specific deletion of the amino acid transporter Slc7a5 has only discrete effects on NK cells, but iron deficiency profoundly impaires NK cell antiviral functions, leading to increased viral loads." (PMID 34508086, 2021).
leiomyoma (1 paper, 2021). A well-circumscribed benign smooth muscle neoplasm characterized by the presence of spindle cells with cigar-shaped nuclei, interlacing fascicles, and a whorled pattern. "Most of the leiomyoma DEGs were found upregulated in F compared to the MF or M; however, some genes, including CDKN1A, L1CAM, SLC7A5, CCND1, IGF1R, and PTHLH, were only increased in MF vs. M and F vs. M comparisons." (PMID 33807176, 2021).
lobular carcinoma (1 paper, 2018). "In addition, SLC7A5 protein expression in lobular carcinoma has a relatively lower mean rank value compared to the other histological subtypes, confirming that deletions involve large segments of q16, which can reflect the BC phenotype." (PMID 29566741, 2018).
lupus (1 paper, 2025). "Follicular helper T (Tfh) cells in lupus‐prone mice display a specific SLC expression signature, including amino acid transporters like Slc7a5, Slc7a10, ASCT2, and LAT1/CD98." (PMID 40567251, 2025).
metastatic cancers (1 paper, 2023). A carcinoma which has spread from the original site of growth to another anatomic site. "Finally, in a comparative study involving multiple primary and metastatic cancers, SLC7A5 and CD98 were the most differentially expressed at primary and metastatic sites by immunohistochemistry (IHC)." (PMID 37829798, 2023).
Neurodevelopmental delay (1 paper, 2018). "Two recently reported Slc7a5 mutations linked to neurodevelopmental delay exhibit a localization defect and have attenuated effects on Kv1.2." (PMID 30356053, 2018).
osteoarthritis (1 paper, 2025). A noninflammatory degenerative joint disease occurring chiefly in older persons, characterized by degeneration of the articular cartilage, hypertrophy of bone at the margins and changes in the synovial membrane. "The nomogram model based on biomarkers demonstrates that SLC3A2 and SLC7A5 have potential diagnostic value in osteoarthritis." (PMID 40420260, 2025).
Pain (1 paper, 2025). An unpleasant sensory and emotional experience associated with actual or potential tissue damage, or described in terms of such damage. "Although no direct literature evidence supports its association with SCI, research has also revealed dysregulation of Slc7a5 and its binding partner Slc3a2 in chronic neuropathic pain conditions where they can serve as potential therapeutic targets." (PMID 39951434, 2025).
pancreatitis (1 paper, 2016). Inflammation of the pancreas. "However, although the expression of many amino acid transporters do change in caerulein-induced pancreatitis,slc7A5/LAT1 expression/immunoreactivity does not41,42." (PMID 27909574, 2016).
papillary thyroid cancer (1 paper, 2015). "We next analyzed whether there was an association between miR-126-3p expression and ADAM9 and SLC7A5 mRNA expression in the TCGA papillary thyroid cancer dataset, and found a significant inverse association with SLC7A5 mRNA expression (r = −0.257, p<0.01) but not with ADAM9 mRNA expression." (PMID 26244545, 2015).
renal tumors (1 paper, 2017). "Specifically, the transcript expressions of AKR1C1, S100A2, PLAU, SLC3A2, TBC1D2, and WIZ were decreased, while expressions of TGM2, SLC7A5, and NMI were increased in renal tumors when compared with non-tumorous control samples." (PMID 29272308, 2017).
scoliosis (1 paper, 2025). A congenital or acquired spinal deformity characterized by lateral curvature of the spine. "Furthermore, the inactivation of slc7a5 has been linked to scoliosis in mice." (PMID 39857294, 2025).
serous ovarian cancer (1 paper, 2022). "Furthermore, SLC7A5 overexpression is significantly associated with Myc expression and elevated in high-grade serous ovarian cancer with grade III-IV concerning the normal tissues." (PMID 36503580, 2022).
spinal muscular atrophy (1 paper, 2026). A motor neuron disease that affect the muscles, and characterized by muscle weakness and atrophy resulting from progressive degeneration and irreversible loss of the anterior horn cells in the spinal cord (i.e., lower motor neurons) and the brain stem nuclei. "Furthermore, multi-cohort transcriptome analyses revealed inactivation of amino acid transport activity along with the downregulation of Slc7a5 expression in motor neurons of spinal muscular atrophy model mice." (PMID 41872133, 2026).
steatosis (1 paper, 2024). Increased lipid within the cytoplasm of cells. "Additionally, subjects with MASH exhibited markedly higher levels of hepatic macrophage SLC7A5 expression than those with simple steatosis." (PMID 39465673, 2024).
thyroid tumor (1 paper, 2019). A benign or malignant neoplasm affecting the thyroid gland. "Also, the use of a MEK1/2 inhibitor significantly reduced Slc7a5 transcription in mouse thyroid tumors model emphasizing the role of the RAS-MEK-ERK pathway in LAT1 regulation." (PMID 31100853, 2019).